MTAP (methylthioadenosine phosphorylase)
Diseases named in the same sentence as MTAP in open-access papers (continued):
Sharing a sentence is not in itself a finding about the gene and the disease.
cancer (continued). "SAM-cooperative orSAM-competitive inhibitors of PRMT5 are not expected to be selectivefor MTAP-null cancers because they inhibit PRMT5 equally in MTAP-nulland MTAP WT cells, ultimately leading to a molecule with limited therapeuticindex." (PMID 38595098, 2024). "The combination of MTAP and MAT2a inhibitors expands this synthetic lethal approach to include MTAP+/+ cancers, especially the remaining 98% of CRCs without the MTAP−/− genotype." (PMID 38000655, 2024). "Restoration of MTAP expression in tumor cells enhances T cell proliferative responses, underscoring MTA’s role in tumor-induced immune evasion and its potential as a target for cancer immunotherapy." (PMID 39461979, 2024). "Subsequently compounds have recently been produced that interact with PRMT5 when bound to MTA, and which selectively target MTAP-negative cancer cells to varying degrees or elicit a synergistic effect in a MTAP-negative background." (PMID 37795443, 2023). "Recently, targeting PRMT5, or MAT2A that impacts PRMT5 activity by producing SAM, has shown promise as a therapeutic strategy in oncology, generating synthetic lethality in MTAP-negative cancers." (PMID 37795443, 2023). "Future generations of drugs that target PRMT5 activity in an MTAP-negative background must focus on maximising their selectivity for inhibiting PRMT5 specifically within the cancer cell (i.e. when PRMT5 is bound to MTA)." (PMID 37795443, 2023). "Regarding DNA methylation, it is worth noting that the promoter regions of BACH2, MTAP, and RUNX1T1 were hypermethylated in NII.clusterB-PNI patients compared with NII.clusterA-PNI patients.These genes act as inhibitory factors in cancer." (PMID 37563649, 2023). "Notably, the specific HCGs shared by both cancer cell lines included CDKN2A, CDKN2B, and MTAP deletions on chromosome 9 and RRAS2 insertions on chromosome 11." (PMID 35570408, 2022). "MTAP gene is often found deleted in various cancer types and not necessarily co‐deleted with CDKN2A." (PMID 35766227, 2022). "MTAP is a tumor suppressor gene near CDKN2A and can be co-deleted in cancer cell lines." (PMID 35764172, 2022). "The physiological role of MTAP is to metabolize MTA and execute tumor suppressive functions including metastasis inhibition in this study, suggesting that MTAP contributes to cancer hallmarks from many aspects and serves as a promising prognostic biomarker." (PMID 35766227, 2022). "PRMTi reduced persistence regardless of the cancer model’s S-methyl-5′-thioadenosine phosphorylase (MTAP) status [a biomarker for sensitivity to PRMTi monotherapy]." (PMID 35089788, 2022). "Consistently in multiple TCGA cancer cohorts, patients whose tumors had homozygous co-deletion of CDKN2A/MTAP and those who had HD of either gene had significantly shorter survival, with no statistical difference observed in the overall survival (OS) time among these three groups." (PMID 34556668, 2021). "Every xenograft established from MTAP-WT (or isogenic MTAP-rescued) cancer cell lines showed intense staining, while all xenografts established from MTAP-deleted cell lines showed no staining." (PMID 34244484, 2021). "MTAP and CDKN2A genes are frequently deleted in human cancers." (PMID 30957015, 2019). "Our results reveal that the kinase activity of RIOK1 is required for the survival of cancer cell lines irrespective of their MTAP status and cast doubt on the therapeutic exploitability of RIOK1 in the context of MTAP-deleted cancers." (PMID 29983885, 2018). "Despite our de-validation of MTAP as a biomarker, that predicts cellular sensitivity to RIOK1 inhibition, other molecular alterations of tumor cells might sensitize cancer cells to the inhibition of RIOK1 kinase activity." (PMID 29983885, 2018). "Specifically to MTAP, this concordance was found in 14 cancer types, an observation that is not much reported in literature yet." (PMID 27556634, 2016).
cancer (continued). "From the analysis of GBM dataset, we could find functional evidences of four targets including CDKN1A, MTAP, KIT and ATM among top 20 ranked miRNA-mRNA interaction pairs have been reported in GBM cancer." (PMID 25079112, 2014). "JNJ64619178, PF06939999, LLY283) and showed no selectivity for MTAP-deleted cancers." (PMID 40157258, 2025). "To determine the source of CXCL10 production, we performed ELISA assays on culture supernatants and confirmed that CXCL10 secretion was significantly reduced in MTAP-KO cells, indicating that cancer cells, not PBMCs, were the primary contributors to CXCL10 levels." (PMID 41246302, 2025). "In MTAP-deleted tumors, increased intracellular concentrations of methylthioadenosine (MTA), the metabolite cleaved by the MTAP enzyme, couple with PRMT5, compete with SAM and, as a result, inhibit PRMT5’s enzymatic activity and contribute to the proposed synthetic lethality in these cancers." (PMID 37502925, 2023). "Furthermore, the PRMT5 inhibitor GSK3230591 is more sensitive in some cancer cells that do not express MTAP." (PMID 36980950, 2023). "It was proven that under dark conditions, the ZnONPs conjugated with methylthioadenosine phosphorylase (MTAP) anticancer drug to safely reach its intended site, and when exposed to ultraviolet A (UVA) radiation they were able to produce ROS, which significantly reduced the viability of cancer cells." (PMID 36629427, 2023). "The carcinomas with BAP1 or MTAP loss included one adenocarcinoma with <80% EZH2 staining and negative CD117 staining, such that the addition of BAP1 and MTAP to a panel of EZH2 (≥80% threshold) and CD117 slightly increased the sensitivity for carcinoma from 92% to 95%." (PMID 37190202, 2023). "Of the 60 cases analyzed, we found that approximately 40% of cases showed a complete lack of MTAP staining in cancer cells, which generally corresponds to the expected MTAP-deleted frequency in GBM41; notably, intense staining was observed in non-malignant stromal cells." (PMID 34244484, 2021). "This work also reveals a combination that may be useful in other cancer types in patients that do not have MTAP deletion." (PMID 31911608, 2020). "Considering that the MTAP gene is frequently codeleted with the adjacent cyclin‐dependent kinase inhibitor 2A (CDKN2A) locus in MM, we assessed whether PRMT5 could represent a therapeutic target also for this cancer type." (PMID 32301278, 2020). "Additionally, methylthioadenosine phosphorylase (MTAP), which functions in the methionine salvage pathway, is located on chromosome 9p21 and is frequently co‐deleted with the tumor suppressor gene cyclin‐dependent kinase inhibitor 2 A in approximately 15% of all cancers." (PMID 40552664, 2025). "Therefore, targeting MAT2A as a possible strategy for treating cancers (especially in MTAP-negative cancers) may reduce tumour growth." (PMID 37795443, 2023). "Moreover, the MTAP‐ and PRMT5‐mediated sDMA modification negatively regulates the stability of vimentin protein via proteasomal degradation, as evidenced by the observations from two independent cohorts, Taiwan Cancer Moonshot proteogenomic data and tissue microarray IHC staining data." (PMID 35766227, 2022). "Therefore, while exon deletions and/or MTAP splicing explain the relative excess transcription of distal ANRIL exons in some cancer cell lines harboring 9p21 deletion, these mechanisms do not explain the decreased transcription of exons 4–12 versus exons 1–3, in any cell line." (PMID 21151960, 2010). "An overwhelming body of evidence suggests that MTAP and the cancer suppressor gene cyclin-dependent kinase inhibitor 2A (CDKN2A) are closely situated and concurrently absent in a subset of cancers." (PMID 40430461, 2025). "When MTDIA is not administered, MTAP metabolizes MTA into adenosine and 5-methylthioribose-1-phosphate (MTR-1-P), allowing for cancer cell proliferation." (PMID 40519286, 2025).
cancer (continued). "Considering the strong difference in MTAP expression between ERG positive and ERG negative cancers, these subgroups were separately analyzed for the role of MTAP expression." (PMID 40554389, 2025). "High MTAP expression levels were strongly related to a high Ki67LI in 2,442 ERG negative but not in 2,229 ERG positive cancers." (PMID 40554389, 2025). "For example, 2+ to 3+ MTAP staining was seen in 78 % of ERG IHC negative, but in 92.8 % of ERG IHC positive cancers." (PMID 40554389, 2025). "Despitethe genetic evidence for a synthetic lethal relationshipbetween PRMT5 and MTAP deletion, the first generationof PRMT5 inhibitors that were developed do not demonstrate selectivityfor MTAP-null cancer cell lines." (PMID 38595098, 2024). "Methylthioadenosine phosphorylase (MTAP), which is related to its metabolism, is often absent in various cancers." (PMID 33816336, 2021). "A promising therapeutic approach to cancer was proposed in 2009 by Lubin and Lubin, based on the addition of MTA to the treatment of MTAP-negative tumors with toxic purine analogs, like 5-fluorouracil (5-FU)." (PMID 26751376, 2016). "MTAP status alone does not determine the sensitivity to RIOK1 inhibition and our data suggest that the kinase activity of RIOK1 is not a relevant therapeutic target for MTAP-deleted cancers." (PMID 29983885, 2018). "The prognostic role of MTAP being independent of all preoperatively and postoperatively available histopathological prognostic features may even point towards a potential clinical application of MTAP measurement in ERG negative cancer." (PMID 40554389, 2025). "Having identified MTAP-WT cells’ presence (i.e., stromal cells, which are predominantly myeloid in GBM) inside MTAP-deleted tumors, we hypothesized that excess MTA secreted from homozygous MTAP-deleted cancer cells may be metabolized by non-malignant MTAP-expressing cells present inside tumors." (PMID 34244484, 2021). "However, it has been reported that MTAP‐deleted tumors did not significantly accumulate MTA in vivo due to metabolism of MTA by MTAP‐expressing stroma, which might lead to a diminished anti‐cancer effect of MRTX1719." (PMID 39711357, 2024). "In cancer cells lacking MTAP, purine synthase mainly depends on the de novo pathway due to the absence of adenine, whereas in normal cells MTA could convert to the adenine metabolite AMP (involved in de novo purine biosynthesis) in the presence of MTAP via the salvage pathway." (PMID 31965001, 2020).
tumor (199 papers, 2004 to 2026). "MTAP‐deficient tumours cannot efficiently catabolise MTA, leading to intracellular MTA accumulation and partial inhibition of PRMT5." (PMID 41537447, 2026). "Homozygous loss of the 9p21 locus encompassing CDKN2A, CDKN2B, and MTAP is the most frequent copy number alteration across tumor types, making it a promising target for precision medicine strategies." (PMID 42000949, 2026). "In tumours with loss of methylthioadenosine phosphorylase (MTAP), inhibition of methionine adenosyltransferase 2α (MAT2A) or protein arginine methyltransferase 5 (PRMT5) also induces a synthetic lethal effect." (PMID 41537447, 2026). "The antitumor effects of PARP inhibitors alone or in combination with either the MTAP inhibitor MTDIA or the PRMT5 inhibitor EPZ015666 were evaluated in solid tumor models, including MTAP-deficient tumor models in vivo." (PMID 42122132, 2026). "In MTAP‐deficient tumor cells, adenine synthesis is solely dependent on de novo biosynthesis, which directly or indirectly involves several druggable enzymes including dihydrofolate reductase and phosphoribosylglycinamide formyltransferase." (PMID 39668577, 2025). "Loss of function mutation in the MTAP gene is caused by homozygous deletion of the 9p21 chromosomal locus that also encompasses the tumor suppressor genes CDKN2A/B." (PMID 41439984, 2025). "In GI cancers, MTAP-null tumors displayed a larger tumor size, higher proliferative index, and were associated with increased risk under the National Institutes of Health (NIH) consensus." (PMID 41439984, 2025). "Lower dose of PARPi combined with MTAP deficiency/inhibition remarkably killed tumor cells in brain metastatic TNBC." (PMID 40590219, 2025). "Tumors that can benefit from targeting MTAP deficiency must be identified by molecular tumor analysis." (PMID 40664803, 2025). "Various molecular and pathomorphological techniques have been used to detect MTAP deletion or loss of protein expression in tumor cells." (PMID 41465382, 2025). "We found that MTAP loss occurs almost exclusively in MSS tumours and it co-occurs with CDK2NA/B and/or other 9p21.3-located gene loss in almost all cases." (PMID 38350716, 2025). "In MTAP-deficient tumor cells, the accumulation of MTA within cells binds to PRMT5, forming the PRMT5/MTA complex." (PMID 39762212, 2025). "Since MTAP is a tumour suppressor gene reported to promote tumour growth by copy number loss, we then focused on 128 cases exhibiting MTAP loss (MTAP loss cohort)." (PMID 38350716, 2025). "The new strategy focuses on regulating the upstream/downstream, such as treating MTAP-deficient tumor cells with L-alanine and antagonizing the A2A receptor or inhibiting CD73 to counteract extracellular adenosine signaling." (PMID 41236698, 2025). "It is important to remember that homozygous MTAP loss is associated with an immunologically “cold” tumor microenvironment." (PMID 41465382, 2025). "We employed murine tumor models and transcriptomic profiling to investigate the immunosuppressive features of MTAP-deficient tumors." (PMID 41246302, 2025). "Tumors that can benefit from targeting MTAP deficiency must be identified by molecular tumor analyses." (PMID 40227771, 2025). "While researchers have seen contradicting perspectives on the effects of MTAP loss on tumorigenesis, most of these studies support the notion that MTAP deficiency contributes to tumor growth and proliferation through different mechanisms." (PMID 41439984, 2025). "Applying the scoring system with the 1% cut‐off, a complete loss of MTAP expression in tumour cells was observed in 13 out of 39 cases (33.33%)." (PMID 40566743, 2025). "Although clinical responses to CB-839 have been variable across tumor types, our findings suggest that MTAP-deficient tumors represent a distinct subset with heightened vulnerability to GLS inhibition." (PMID 41246302, 2025).
tumor (continued). "utilised SERS to profile secreted purines in methylthioadenosine phosphorylase‐deficient tumours (corroborated by liquid chromatography‐mass spectrometry measurements and RNA sequencing) revealing a unique paracrine crosstalk in the tumour microenvironment." (PMID 40999586, 2025). "Loss of MTAP is intricately associated with multiple biological pathways including metabolism, the tumor microenvironment, and tumor progression." (PMID 41439984, 2025). "In view of the proposed role of MTAP deficiency as a predictor of poor response to CPIs, we made use of the tumor microenvironment data from earlier studies to evaluate the possible interactions of MTAP deficiency with antitumor immunity." (PMID 39668577, 2025). "We have demonstrated that MR enhances the combination effect of PARPi and MTAP deficiency/inhibition in tumor growth suppression." (PMID 40590219, 2025). "Third, the analysis was underpowered to distinguish small-effect size differences within individual tumour types, especially given the small numerosity of MTAP loss CRC and BTC." (PMID 38350716, 2025). "Our findings provide new insight into how tumor metabolism modulates immune resistance associated with MTAP loss, with potential implications for enhancing tumor immunogenicity and expanding the efficacy of immune-based therapies." (PMID 41246302, 2025). "Our findings further support this concept: GLS inhibition via CB-839 not only selectively impaired MTAP-deficient tumor growth but also restored CXCL10 expression, particularly in immune co-culture." (PMID 41246302, 2025). "Given the highly homogeneous nature of MTAP deficiency, this difference cannot be explained by the higher number of samples (n = 5) that were analyzed per tumor in our “heterogeneity TMA” or the whole section approach in 41 cases." (PMID 40664803, 2025). "The worse OS of MTAP‐deficient as compared to MTAP‐proficient tumors is also consistent with a role for MTAP loss in tumor progression." (PMID 39668577, 2025). "Growing evidence indicates that MTAP deficiency profoundly reshapes the tumor immune microenvironment, driving a spectrum of immunosuppressive mechanisms." (PMID 41465382, 2025). "Tumors with 9p21 deletions and loss of MTAP expression were further characterized by low numbers of PD‐L1‐positive tumor cells (p < 0.0001 each) and macrophages (p = 0.0020 for MTA IHC; p < 0.0001 for 9p21 FISH)." (PMID 39668577, 2025). "Among genomic alterations deemed potentially targetable, whereby an approved targeted therapy exists in the same or other tumor types, statistically significant differences were observed between MTAP-loss versus MTAP-intact profiles." (PMID 38330461, 2024). "MTAP deletion is linked to the mechanism of action requiring the accumulation of MTA within the tumor." (PMID 38000655, 2024). "Positive PD-L1 tumor cell expression was less frequent among MTAP-loss versus MTAP-intact IHCC tumors (23.2% vs 31.2%, P = .017)." (PMID 38330461, 2024). "When simulating the advanced stage of tumor, MTAP‐deficient cells were inoculated in the lower layer while MTAP‐normal expression cells in the upper layer." (PMID 39711357, 2024). "The large amount of MTA synthesized by MTAP‐deficient tumor cells is constantly secreted outside the cell, resulting in much higher levels of extracellular MTA than intracellular." (PMID 39711357, 2024). "Significant differences in the prevalence of potentially targetable genomic alterations (ATM, BRAF, BRCA2, ERBB2, IDH1, PIK3CA, and PTEN) were observed in MTAP-loss tumors and varied according to tumor type." (PMID 38330461, 2024). "MTA-cooperative PRMT5 inhibitors have the ability to maintain potent anti-tumor activities, but avoid dose-limiting hematology toxicity in cancer patients harboring homozygous loss of MTAP as shown by MRTX1719 and AMG193’s clinical studies." (PMID 39655075, 2024). "Tumour cells exhibit frequent loss of methylthioadenosine phosphorylase (MTAP), which leads to the accumulation of its substrate MTA." (PMID 38969865, 2024).